CD83 (CD83 molecule)
Diseases named in the same sentence as CD83 in open-access papers (continued):
Sharing a sentence is not in itself a finding about the gene and the disease.
tumor (continued). "Conversely, patients with a more effective anti-tumor response (mature CD83) would also be likely to respond to NAC (partial response vs. no response), resulting in better outcomes (lower risk of relapse, and longer OS)." (PMID 36765559, 2023). "Studies on different neoplasms have shown that the density of CD83+ cells was lower in cancerous tissues compared to healthy controls, and it decreased as the disease advanced." (PMID 36768258, 2023). "By the analysis of 55 patients with GC, cytoplasmic TGF-β1 expression was observed in tumor cells from 76.4% of cases, and low CD83+ DCs in the tumor border was found in 100% of tumors with TGF-β1 expression." (PMID 35619702, 2022). "Analysis of the relationship between risk score and the expression of crucial immune checkpoint genes revealed that high-risk patients had higher CTLA4, CD83, B3H7, OX40L, and GEM levels in the tumor microenvironment." (PMID 33718151, 2021). "Although expression of CD83 on immune cells has been described extensively, to the best of our knowledge CD83 expression on tumor cells and its role in the induction of anti-tumor responses in this context has not been elucidated in the literature." (PMID 34831294, 2021). "In HCC patients, lower numbers of DCs expressing CD83, which is considered a maturation marker, were observed in tumor lesions, as compared to healthy controls." (PMID 34062821, 2021). "To show the distribution of aDCs in DLBCL tissues, we also detected the expression of the aDC marker CD83 on tumor biopsies of DLBCL patients." (PMID 34001679, 2021). "Regarding DC positioning inside the tumor zones, as is the case with T cells, mature CD83+ DCs stay predominantly outside of the tumor center, with immature CD1a+ DCs recruited into the tumor." (PMID 32781527, 2020). "Taken together, these data indicated the importance of the CD83 in the promotion of the growth proliferation and spheroid formation in vitro, as well as in vivo tumor growth." (PMID 32823589, 2020). "Tumor-infiltrating CD83-positive DCs are of great importance in initiating the primary antitumor immune response and are confirmed as an independent, immunologic prognostic parameter for survival in patients with various types of cancers." (PMID 32823589, 2020). "In conclusion, our research demonstrated CD83 expression in MCL cell lines and primary tumor cells and showed the anti‐CD83 ADC is a possible therapy for CD83+ MCL treatment." (PMID 32685149, 2020). "Prior studies have shown that CD83 is a downstream target of NFkB, and can be detected on solid and hematologic malignancies, and has been shown to influence the tumor microenvironment." (PMID 32708981, 2020). "Phenotypic maturation and activation: The CD83 maturation marker was upregulated on DCs when co-cultured with virus-infected tumor cells." (PMID 31969562, 2020). "RNA sequencing on a subset of tumor samples identified that CD83 was highly expressed in our responder group." (PMID 32708981, 2020). "The correlation between clinical response and ex vivo levels prior therapy of plasmacytoid DC CD83+ (a cell that produces type-I IFN important to activate anti-tumor responses) suggests this marker as useful for predicting clinical response to treatment." (PMID 29334915, 2018). "Amongst other parameters, DC maturation is also inhibited by the tumor microenvironment, which is characterized by a reduced expression of CD83 and CD86." (PMID 28719632, 2017). "Tumor CD83 expression suggested that both viruses were able to recruit mature dendritic cells with equal efficiency." (PMID 29123084, 2017). "There was also a significantly reduced % of circulating mDC1shigh and pDCshigh and reduced expression of HLA-DR, CD40, and CD83 on mDC1shigh and HLA-DR on pDCshigh in those patients whose tumours showed a PPR to NAC." (PMID 28913366, 2017). "In the normal colorectal mucous membrane adjacent to the cancerous tumor we observed quite numerous CD83 positive cells." (PMID 26839537, 2016).
tumor (continued). "Here, we showed that GNPs impaired the up-regulation of CD83 by DCs, which is crucial for the stability of their maturation in an IL-10-enriched immunosuppressive tumor micro-environment." (PMID 24802102, 2014). "Activated CD83+ B cells are capable of effective tumor-antigen presentation via MHC II and it is possible that B cells in the Adherence DC vaccine potentiate immunogenicity." (PMID 25475068, 2014). "We found that CD1a- and CD83-positive cells were dispersed with variable density and in OC CD31+ vessel numbers were positively correlated with CD83+ dendritic cells in tumour stroma (R = 0.847, p = 0.016)." (PMID 26019537, 2014). "Accompanying the tumor-associated shifts in the CD1a/CD14 frequencies, CD83 frequencies also shifted in concordance with a mature state of the CD1a+ DC and an immature state of the CD14+ DC." (PMID 23875023, 2013). "The main aim of the present study was to assess the expression of B7H1, B7H4, CD200 and CD200R on CD83+ Mo-DC, pulsed with autologous tumor cell lysates (aTCL), of patients who suffer from LC in comparison to healthy donors (HD)." (PMID 23632869, 2013). "The phenotypical analysis of DC pulsed with the “new method-tumor lysate” demonstrated that the expression of CD83 molecule is higher and more homogeneous than in DC activated with the “classical method-tumor lysate”." (PMID 23284979, 2012). "Their results demonstrated a higher number of mature CD83+ DCs in tumour tissue of responders following cytokine treatment." (PMID 20969772, 2010). "Inhibition of HSP-70 on spheroids treated with 5-ALA-PDT prior to evaluation of tumor material uptake from spheroids significantly inhibited tumor antigen uptake and DC maturation, as indicated by a significant decrease in the frequency of CD83+ mature DCs." (PMID 40807266, 2025). "Samples exhibiting low CD83 expression signatures exhibited a positive correlation with immunosuppressive gene sets pertaining to regulatory T cells, TAMs, and PD-1–PD-L1 interactions, suggesting that low levels of CD83 expression by tumor cells promote immunosuppressive phenotypes." (PMID 39601621, 2024). "However, in the CD83OE tumors, these effects seem to be mitigated by cell-extrinsic mechanisms that suppress CD83-induced proliferation to slow tumor progression in vivo." (PMID 39601621, 2024). "To examine the expression of CD83 in tumor-infiltrating CAR-T cells compared with T cells outside the tumor, we administered anti-mesothelin CAR-T cells intratumorally into subcutaneous A375-mesothelin tumors and uncultured T cells from the same donor intravenously." (PMID 36906640, 2023). "Finally, we examined the distribution of CD83 expression in endogenous human tumor-infiltrating T cells." (PMID 36906640, 2023). "Many authors observed negative associations between DC83+ cell counts and tumor size or metastatic occurrence and claimed that the density of DCs CD83+ within cancerous tissue was well suited for predicting survival." (PMID 36768258, 2023). "Furthermore, Hodgkin lymphoma cells express CD83 to subvert anti-tumor T cell responses, in part by secretion of sCD83." (PMID 35054916, 2022). "Interestingly, CD83+ lymphoma cells can transfer mCD83 onto surrounding T cells, thereby subverting their anti-tumor activity." (PMID 35054916, 2022). "The content of mature dendritic cells (CD80+CD83+) in the tumor node was assessed." (PMID 35693632, 2022). "The CD83 expression in cancer cells facilitates the tumor growth." (PMID 35675043, 2022). "Patients with a low density of tumor-infiltrating CD83+ DCs had shorter survival rates, Therefore, tumor-infiltrating DCs might be important in initiating the primary anti-tumor immune response." (PMID 35619702, 2022). "In contrast, dense CD83+ DC infiltrate was observed in luminal tumours." (PMID 33919875, 2021).
tumor (continued). "Notably, all six expression-based markers for human TI-Tregs, TIGIT, TNFRSF9, ICOS, CCR8, CD83, and CCRL2, were ranked within the top 10%, which indicates that they are likely to play major roles in tumor-associated Treg functions." (PMID 33598101, 2021). "In another study, CD83+ DCs were mainly found at the invasive front of the tumor." (PMID 34062821, 2021). "Immunophenotyping tumour-infiltrating DCs across GI cancers would be important to confirm if this effect occurs in vivo, although quantification of maturation markers, including CD83, can be difficult." (PMID 32552799, 2020). "Similar to subcutaneous HCC models, we found a higher proportion of mature DCs in tumor and paracancerous tissue in orthotopically transplanted hepatomas in Fgl2−/− mice along with decreased presentation of CD31 on DCs from both tissues and elevated CD83 expression in tumor tissue." (PMID 31409352, 2019). "Furthermore, the number of CD83+ mature DCs in the primary tumor of CRC patients correlated with the presence of tumor cells in blood and lymph vessels as assessed by histology, and local lymph node metastases." (PMID 30200242, 2018). "Before loading with tumour lysate, DCs were characterized by flow cytometry to analyse the expression of MHC class I and II molecules, costimulatory molecules (CD86, CD80, CD40), and markers associated with maturation (CD83, CCR7, PD-L1)." (PMID 26795765, 2016). "However, in the front of the tumor an increase of CD83 positive cell numbers of even up to 17 in the field of view (on average around 5 mature dendritic cells) was observed." (PMID 26839537, 2016). "Interestingly, we found that the T cell costimulatory molecules CD80 and CD86 and the mature molecule CD83 were substantially upregulated on the tumor-activated γδ T cells, along with the obvious increased expression of HLA-DR (n = 9)." (PMID 24741609, 2014). "Moreover, based on the expression of CD83, which is a marker of mature dendritic cells, NeuGcGM3 appeared to be involved in tumor-induced dendritic cell suppression." (PMID 23162791, 2012). "Additionally, we also observed a significant increase in the total percentage of mature DCs (CD11c+ MHCII+ CD83+) both within the tumor and the DLNs in comparison to groups receiving PBS or MRF alone." (PMID 23133545, 2012). "As a further confirmation of the improvement provide by the semi-automated method of tumor lysis, we observed a significant increase in CD83 expression on DC activated with the tumor lysate produced following the “new method” rather than the “classical method” tumor lysate." (PMID 23284979, 2012). "Even in the tumour tissues, only rare CD83+ DCs were observed." (PMID 20969772, 2010). "At day 5, U-251 tumor cell lysate was added to the generated immature DCs and by day 6, cell started exhibiting morphological changes that were accompanied with the further changes in the expression of DCs' phenotypical markers such as CD83, CD86, HLA-DR." (PMID 20195476, 2010). "Moreover, in vitro tumour supernatants are able to promote rapid maturation of DCs with upregulation of CD83 molecule expression." (PMID 14562018, 2003). "Markers of DC differentiation/activation, such as CD83 and other molecules, may therefore be more accurate in establishing the true capacity for antigen presentation within the tumour microenvironment." (PMID 12888826, 2003). "In fact, we found that exposure of in vitro maturing DCs to spermine enhanced the expression of CD83, suggesting that this tumour-derived polyamine could be involved in the phenotypic maturation of PB DCs observed in vivo." (PMID 14562018, 2003). "Importantly, tumor-derived CD83 could mediate communication with T cells, altering the immune microenvironment to potentially enhance immune-related tumor clearance." (PMID 39601621, 2024). "CD83+CCR7- DCs within the human HCC tumor could be detected." (PMID 35619702, 2022). "CD83+ mature myeloid DCs could be observed in all tumour cases investigated." (PMID 20969772, 2010).
tumor (continued). "CD11c+/CD83+/MHC‐II+ DCs in the spleen, tumour‐draining lymph nodes, and tumour‐infiltrating lymphocytes were 1.5–2 times more abundant in the magnolol plus RT group compared to the control group." (PMID 40830825, 2025). "Even in the CD83-negative cells tumor cells, there was increased signaling with CD45-positive immune cells and T cells in high CD83 score tumors compared with low CD83 tumors." (PMID 39601621, 2024). "To test if these co-stimulatory molecules played a role in local and abscopal tumor control in hRT/lena-treated mice, we blocked CD70, CD83, and CD86 during hRT/lena treatment by co-administration of blocking antibodies." (PMID 38646638, 2024). "Immunostaining for IDH1R132H and CD83 in an IDHmut patient sample confirmed the existence of these CD83+CD45– tumor cells, which we termed antigen presenting–like tumor cells (ALT)." (PMID 39601621, 2024). "Individual positive regulatory co-stimulatory molecules (CD70, CD83, CD86) were mainly upregulated in the irradiated tumor of hRT/lena-treated mice." (PMID 38646638, 2024). "We describe a unique tumor-infiltrating immune profile with high levels of lymphocytes (CD4, FOXP3) and dendritic cells (CD21, CD1a and CD83) that are valuable prognostic factors in post-NAC TNBC patients." (PMID 36765559, 2023). "Activated GC B cell genes like CD83 and CD40 were highly expressed in tumour‐free TDLN, whereas the expression level of immature B cell markers like CD27 was higher in PT." (PMID 37491740, 2023). "Of note, the transition to HLA-DR+ neutrophils was accompanied by a shift toward the identified TAN signature (elevated expression of CD83 and LOX-1 and lower expression of CD181 [CXCR1], CD62L [SELL], and CD16) in neutrophils derived from NSCLC tumor tissue." (PMID 36368318, 2022). "The chemokine, CCL4, and the T cells activator, CD83, were also found to be upregulated in the HPV+ tumour-T cell interactions." (PMID 36420261, 2022). "In contrast, the CD209+ CD83− NTLS-DC subpopulation has an immunosuppressive phenotype and develops under the stimulation of various tumor-derived factors, including IL-10, TGF-β, prostaglandin E2 (PGE2), and chemokines." (PMID 33746989, 2021). "An integrated gene profile and functional analysis of tumor-infiltrating immune cell (TIC) proportions revealed that DC activation markers (CD80, CD83, CD86) were positively correlated with CXCL8 expression." (PMID 34025668, 2021). "In this study, we consistently observed high expression of both HLA-DR and CD40 by most tumor-infiltrating B cells, as well as CD80, CD83, and CD86 expression by a subset of B cells." (PMID 33763071, 2021). "The significantly higher DC densities were observed at the tumour’s invasive margin for LAMP3+, CD123+, CD83+ and DC-SIGN+ cells, in comparison with intratumoural area (p < 0.001 for each DC subpopulation)." (PMID 33919875, 2021). "Matured DCs (≥ 60% upregulation of CD80, CD86, CD83, and CCR7) produced high levels of the Th1 effector cytokine, IL12-p70 (1.2 ng/ml; p < 0.0001), compared to DCs pulsed with tumour lysate, or matured with an interferon-containing cocktail alone." (PMID 30283982, 2019). "mDCs able to present tumor antigens to T cells were confirmed by the presence of surface markers CD80, CD83, and CD86 and HLA-ABC and HLA-DR antigens." (PMID 31546936, 2019). "In our study incubation of DC with tumor supernatant significantly lowered the expression of CD83, CD86 and HLA-DR, confirming the immunosuppressive effects of the tumor." (PMID 28719632, 2017). "Tumour lysate pulsing resulted in a significant increase in the expression of MHC and costimulatory molecules as well as of CD83, a marker of phenotypical maturation, CD40 and CCR7." (PMID 26795765, 2016). "Flow cytometric analysis of the harvested tumor lysate-loaded DCs revealed a phenotype characteristic of mature DCs with high expression of CD40, CD80, CD83, CD86, HLA-ABC, HLA-DR, and CCR7." (PMID 25694811, 2014).
tumor (continued). "Tumour markers like ezrin, HSP90, CD83, and others also reveal a potential as biomarkers of BCG treatment response." (PMID 22919375, 2012). "Pre-treatment of monocyte derived dendritic cells with this tumour conditioned media inhibited the up-regulation of CD86, CD83, CD54 and HLA-DR in response to LPS, enhancing IL-10 while reducing IL-12p70 secretion." (PMID 22125641, 2011). "These immune responses occur in the immune cells surrounding the tumor tissue and in lymph nodes infiltrated by tumor cells, where mature CD83+ dendritic cells are fewer in number compared to non-infiltrated lymph nodes." (PMID 41596472, 2026). "Based on mIHC assay, we revealed abundant CD83+ and CD86+ antigen-presenting cells within peritumoral stroma of pre- and post-treatment samples of responders, indicative of enhanced anti-tumor immunity." (PMID 41355948, 2026). "CHRNA7KO mice had decreased levels of MHCII, CD11c, and CD83 expression in CD11b+ cell subsets, while no overall changes in the numbers of CD11b+ or F4/80+ tumor macrophages were observed." (PMID 40653990, 2025). "Thus, immunosuppressive tumor cytokines and AhR stimulation promote CD83 downregulation and generation of CD83- IDO1+LCs (immature tolerogenic LCs) and/or CD83- IDO1-LCs (real immature LCs)." (PMID 38791968, 2024). "Interestingly, most CIDGS-related genes, such as XRCC6, ST13, PES1, EFHD2, APOL2, ACTR2, and CDCP1, were markedly upregulated in HNSCC tumor samples, whereas several other genes, such as MARCO, MRC1, and CD83, were upregulated in healthy samples." (PMID 38666027, 2024). "Many phagocytosing immune cells actively surveil the TME, therefore to ensure CD83+ tumor cells were not an artifact of this process, we assessed CD83+ tumor cells that did not express the immune lineage marker CD45." (PMID 39601621, 2024). "Upregulation in both irradiated and non-irradiated (abscopal) tumor was found when all three co-stimulatory molecules were stained together (CD70+ CD83+ CD86+ DCs)." (PMID 38646638, 2024). "Since CD83+ T cells included both CCR7+ and CCR7− cells, and CD83− cells were mostly negative for CCR7 as was seen in the tumor model, we isolated three populations (CD83+CCR7+, CD83−CCR7+, and CD83− cells) and restimulated them in vitro." (PMID 36906640, 2023). "DC cocultured with UVM cells showed reduced expression of CD1a and CD83, which failed to activate T cells for immune response, revealing the possibility of tumor-pulsed dendritic cell vaccines as therapeutic measures for UVM." (PMID 36568076, 2022). "Our data showed no influence on tumor infiltration by mature (CD83+) and immature (CD1a+) DCs on the survival of patients with TSCC." (PMID 35584505, 2022). "We were not able to confirm these results, but we demonstrated denser CD83+ DC infiltrate in luminal tumours compared to non-luminal ones." (PMID 33919875, 2021). "Strikingly, the higher dose of exosomes derived from LOAd703-infected tumor cells could mature DCs, as seen by upregulation of MHC class I (HLA-ABC), CD86, and CD83 (p ≤ 0.05)." (PMID 33738337, 2021). "Mature DCs loaded with PAM lysates showed an increased maturation potential, as estimated by their increased expression of CD83, CD86, CD40, IL-12/IL-10 production, and attenuated PDL1 and ILT-4 expression, compared to the DCs treated with control tumor lysates." (PMID 33915703, 2021). "Secreted factors from OAC tumour biopsies can significantly reduce CD83 expression on dendritic cells but not the expression of PD-L1, CD40, HLA-DR and CD54." (PMID 32694701, 2020). "Notably, tumor-derived pDCs responded to TLR stimulation with upregulation of CD69, CD86, and CD83 after 4 h." (PMID 33013879, 2020). "The number of dendritic cells per tumor area was significantly higher in EBVaGC cases than in EBV-negative GC cases for any of the DC markers (p < 0.001 for Langerin, CD1a, CD83, CD86, and BDCA-2, and p < 0.05 for S100, respectively, determined by using a Wilcoxon rank sum test)." (PMID 33198173, 2020).